CHGA (chromogranin A)
Diseases named in the same sentence as CHGA in open-access papers (continued):
Sharing a sentence is not in itself a finding about the gene and the disease.
tumor (continued). "Furthermore, NEPC cells scattered in an AdPC tumor with neuroendocrine differentiation also displayed high STMN1 expression, as indicated by dual immunofluorescence staining for the NE marker Chromogranin A (CHGA) and STMN1." (PMID 39711570, 2024). "Noteworthily, UCHL1 and CHGA have never been implicated in migration and invasion of CRC and tumour growth in nude mice xenograft models of cancer." (PMID 37246623, 2023). "Immunohistochemically, the tumor cells were positive for CK, calretinin, D2-40, WT-1, and vimentin, and negative for Paird box 8, synaptophysin, chromogranin-A, inhibin-α, S-100, Melan-A, HMB45, and CD34." (PMID 38115250, 2023). "The insulin-secreting tumor was 10-mm in diameter and consisted microscopically of atypical cells positive for chromogranin A, synaptophysin and insulin but negative for glucagon and somatostatin." (PMID 37563593, 2023). "CHGA and UCHL1 expression were related to tumour size and tumour stage LNM in CRC." (PMID 37246623, 2023). "In addition, focal staining for Melan-A, weak chromogranin A staining, partial, patchy desmin staining and weak heterogonous NSE immunoreactivity was detected in the tumor cells." (PMID 35501497, 2023). "Immunohistochemical detection of the neuroendocrine markers chromogranin A or CGRP as well as the expression of TTF-1 or the absence of p63 that were observed in subcutaneous tumors corroborated the presence of metastatic tumor cells." (PMID 37894963, 2023). "Alternatively, a mechanism of the Wnt/β‐catenin signalling pathway may upregulate CHGA and UCHL1 at the transcriptional level and to influence the processes of tumour microenvironment formation and metastasis." (PMID 37246623, 2023). "Immunohistochemical examinations demonstrated positive staining of the tumor cells for cytokeratin, synaptophysin and chromogranin A, and negative for smooth muscle actin, desmin, S-100." (PMID 38152101, 2023). "The ‘classical’ tumour markers chromogranin A and 5-HIAA proved non-informative for confirmation of the diagnosis, disease stage, and/or follow-up." (PMID 37760408, 2023). "The functional role of CHGA and UCHL1 in tumour growth, migration and invasion of CRC is still unknown." (PMID 37246623, 2023). "In the tumor tissues of NEPC patients, AR signaling is low or lost, and such typical NE markers as neuronal-specific enolase 2 (ENO2), synaptophysin (SYP), NCAM1 and chromogranin A(CHGA) are remarkably elevated." (PMID 37563661, 2023). "According to histological assessments, there were no statistical differences in tumor grade, mitotic rate, lymphovascular invasion, and immunohistochemical staining for chromogranin A (CgA) and synaptophysin (Syn) between the two groups (all P > 0.05)." (PMID 36632622, 2022). "However, two out of three of these patients had cancer progression on cross-sectional imaging and rising serum chromogranin-A levels, indicating that a rising 5-HIAA level post cardiac surgery warrants investigation for tumor progression." (PMID 35465425, 2022). "Immunohistochemical examination of the section indicating solid-nest growth revealed the tumor cells to test positive for synaptophysin, CD56, and partially positive for chromogranin A. The growth had Ki-67 index > 20%, indicating the existence of the NEC component." (PMID 35235080, 2022). "Most tumor cells of the neuroendocrine component were immunoreactive for CAM.5.2, cytokeratin (CK) 7, CK AE1/AE3, synaptophysin, chromogranin A, parathormone, GATA3, and parafibromin, whilst they were negative for thyroglobulin, TTF1, calcitonin, glucagon, and S100." (PMID 32506375, 2021). "Immunohistochemistry showed that the tumor cells were positive for calcitonin, chromogranin A, synaptophysin, CD56, and TTF-1, but negative for other lineage-specific markers." (PMID 34838061, 2021).
tumor (continued). "Immunohistochemically, tumor cells were negative for thyroid transcription factor-1, negative for thyroglobulin, negative for chromogranin A (positive for normal parathyroid tissue within the nodule), positive for PTH, and positive for parafibromin." (PMID 33978837, 2021). "Chromogranin A is specific for neuroendocrine cells but does not discriminate between hyperplasia and neoplasia." (PMID 31963924, 2020). "Traditionally, several plasma, serum, and urine markers have been evaluated as predictors of tumor progression in NETs, including 5-hydroxy indole acetic acid (5-HIAA), chromogranin A (CgA), serotonin, neuron-specific enolase (NSE), neurokinin A, E-cadherin, or neuropeptide K." (PMID 32563832, 2020). "The tumor cells were now negative for Chromogranin A but positive for synaptophysin and pan-cytokeratins, and the Ki-67 index was consistently 90% in all three metastatic lesions." (PMID 32854635, 2020). "A few tissues within the tumor express synaptophysin without chromogranin-A, which is a neuroendocrine marker." (PMID 33157911, 2020). "data on tumor markers (i.e., Chromogranin A) were available in a minority of patients and were thus not reported in the final analysis." (PMID 31242670, 2019). "Immunohistochemistry revealed that the majority of tumor cells were positive for chromogranin A (CgA) and Synaptophysin (Syn), but negative for cytokeratin markers (CKs), including CK7 and CK20." (PMID 31038858, 2019). "Chromogranin A serves as biomarker in patients with GEP-NETs and may also reflect tumor burden in patients with liver metastases." (PMID 31237925, 2019). "Immunohistochemical examination revealed that the tumor cells were positive for the neuroendocrine markers chromogranin A and synaptophysin and negative for gastrin, glucagon, somatostatin, VIP, insulin, and serotonin." (PMID 29218566, 2018). "Tumor cells were negative for neurofilament (surrounding CNS tissue stained positive) and chromogranin A. Glial fibrillary acid protein (GFAP) was observed in 20% of the tumor cells." (PMID 29908563, 2018). "Repeated chromogranin A measurements can be made to assess tumour response, although the results should not be used to determine management [IIIC]." (PMID 28194228, 2017). "Immunohistochemistry revealed that the tumor was positive for S-100 and negative for synaptophysin, chromogranin A, and pan keratin (AE1/AE3)." (PMID 27832806, 2016). "Immunohistochemically, the resected specimen revealed that the tumor and the lymph node metastasis were positive for chromogranin A and CD56 and negative for synaptophysin." (PMID 27457078, 2016). "Immunohistochemically, the tumor stained positive for CD56, chromogranin A, and synaptophysin." (PMID 27457078, 2016). "The tumor cells showed positive immunoreactivity for synaptophysin, chromogranin A, ER, PgR, and bcl-2 and negative (or almost negative) immunoreactivity for HER-2." (PMID 28105053, 2016). "We also observed that the tumor was positive for S-100 which is mainly present in neurons, chondrocytes, adipocytes, and pigment cells, and negative for synaptophysin, chromogranin A, and pan keratin (AE1/AE3)." (PMID 27832806, 2016). "A correlation between chromogranin A expression and radiologic tumour response was not carried out because many chromogranin A measurements were missing." (PMID 26138480, 2015). "The dosage of chromogranin A is short specificity and sensitivity but can be useful in case of non-functional tumor and for the follow-up of the patients." (PMID 26600911, 2015). "Immunohistochemically, the tumor cells were positive for prolactin, chromogranin-A, and synaptophysin, but were negative for glial fibrillary acidic protein, S-100 protein, epithelial membrane antigen, and vimentin." (PMID 26228535, 2015).
tumor (continued). "Serum chromogranin A levels are elevated in 80% of patients with NET regardless of tumor location and correlate with disease burden." (PMID 25810937, 2015). "Pathological analysis of the resected submucosal 1.8 cm tumour of the Meckel diverticulum confirmed a well differentiated neuro-endocrine tumour (grade I), whereas immunohistochemistry was positive for ACTH, chromogranin A and synaptophysin; Ki-67 score was < 1 %." (PMID 26610855, 2015). "At immunohistochemical examination tumor cells stained positive with chromogranin A and synaptophysin antibodies and were negative for hepatocyte, AFP, and CD56 antibodies." (PMID 24653852, 2014). "All of the 29 tested carcinomas were negative for chromogranin A and one of the 29 cases stained moderately and focally (<10% of tumor cells) for synaptophysin." (PMID 24701575, 2014). "Measurement of a full fasting gut hormone profile showed elevated chromogranin A but was otherwise normal, consistent with a non-functional tumour." (PMID 25151270, 2014). "The tumor cells were identified to be positive for synaptophysin, chromogranin A and cluster of differentiation 56, but were negative for Ki-67." (PMID 24765196, 2014). "GSCC is unique in its positive reactions to synaptophysin and chromogranin A, although 10-20% of GSCCs demonstrate negative reactions for these tumor markers." (PMID 24099520, 2013). "Most of the tumor cells which were identified by nuclear expression of SV40 TAg in parallel tissue sections of 30- and 90-day-old CEA424-SV40 TAg-transgenic mice strongly expressed chromogranin A." (PMID 22253802, 2012). "Tumour cells were immunoreactive for chromogranin-A and synaptophysin, but not for CD56 or serotonin." (PMID 21435225, 2011). "Chromogranin A (CgA) has replaced the 24-h urine collection of 5-hydroxyindoleacetic acid and has become the most important tumour marker in the monitoring of NET during and after treatment and is recommended by the European NeuroEndocrine Tumor Society." (PMID 21989216, 2011). "Histology showed the lesion to be a completely excised, well differentiated NET with relatively uniform tumour cells, immunopositive for chromogranin-A, synaptophysin and CD56; no detectable mitoses were seen." (PMID 21435225, 2011). "All tumours producing hCGderived molecules were negative for the concomitantly analyzed neuroendocrine markers chromogranin A, synaptophysin and neuron-specific enolase (NSE)." (PMID 21918707, 2010). "Chromogranin A immunostaining was negative and only 1% of the tumours were synaptophysin immunopositive." (PMID 20462442, 2010). "Surgical resection of the tumor with postoperative negative octreotide scan, decreasing chromogranin A level, and 5-HIAA within normal values reflects a favorable prognosis." (PMID 18021452, 2007). "[68Ga]-DOTATOC PET/CT may be a valuable technique for estimating the functional tumor burden, given the lack of clinical indices that correlate with elevated serum chromogranin A level in patients with pNETs." (PMID 40361414, 2025). "Tumour markers, including chromogranin A and serum gastrin, could not be assessed due to unavailability." (PMID 41169289, 2025). "Since GCG encodes the precursor of GLP-1, the observed reduction in GCG and other key EEC markers (CHGA, NEUROD1, PYY) in tumor tissue, combined with these external clinical data, suggests that EECs and incretin hormones may exert an anti-tumor role in colorectal carcinogenesis." (PMID 41303610, 2025). "Contrasting with chromogranin A’s variability, serum visfatin may present a more consistent option, independent of tumor features." (PMID 40723227, 2025). "NET biomarkers can be divided into non-specific (chromogranin A, neuron-specific enolase, and beta-human chorionic gonadotropin) and tumor-specific analytes (insulin, gastrin, vasoactive intestinal peptide, glucagon, somatostatin, serotonin, and 5-hydroxyindoleacetic acid)." (PMID 40723227, 2025).
tumor (continued). "After completion of radiotherapy an increase of positive CTC markers – especially the epithelial (CK19, EpCAM) and neuroendocrine (SYP, CHGA) transcripts was observed, which led us to the hypothesis of increased CTC shedding due to the disruption of the tumor by radiation therapy." (PMID 39305397, 2024). "The mitotic rate of NECs is >20/mm2, and they usually stain positive for synaptophysin but may be negative for chromogranin A. EUS may be done to look for the depth of the tumor and local lymph node involvement." (PMID 39161532, 2024). "Concurrently, the strong positivity for smooth muscle actin, alongside the negativity for CD117, chromogranin A, and synaptophysin, suggests that the tumor is derived from smooth muscle cells rather than from interstitial cells of Cajal or neuroendocrine cells." (PMID 39896188, 2024). "Chromogranin A in both patients and tumor markers done in one of the patients were negative." (PMID 39430421, 2024). "Moreover, this study shows that tumor size, mitotic count, and chromogranin A level are not correlated with recurrence." (PMID 36979807, 2023). "Due to its extremely small tumor size, immunohistochemical staining for chromogranin A or synaptophysin could not be conducted." (PMID 37878146, 2023). "The tumor was positive for chromogranin A staining but negative for tyrosine hydroxylase." (PMID 36945070, 2023). "Tumor size, mitotic count, and serum chromogranin A levels did not correlate with recurrence." (PMID 36979807, 2023). "Immunohistochemically, the tumor cells were positive for paired-box gene 8, thyroid transcription factor-1, and negative for thyroglobulin, calcitonin, and chromogranin A. Inter- and intra-trabecular accumulation of type IV collagen-positive materials was not demonstrated." (PMID 37340328, 2023). "Furthermore, SST4 expression in the tumours negatively correlated with serum serotonin values (rsp = − 0.322; p = 0.023), but not with serum chromogranin A (CgA) values (rsp = − 0.106; p = 0.380)." (PMID 36042228, 2022). "Further, CHGA, which plays a role in neuroendocrine secretion, BLRVB, a broad specificity oxidoreductase that is also involved in heme metabolism, and CAMTA2, which is possibly involved in cardiac growth and tumor suppression, were also all positively selected in pinnipeds but not in cetaceans." (PMID 35615068, 2022). "Notably, endometrial cancer cells infiltrated into lymphatic vessels are also positive for chromogranin A. Additionally, the tumor cells were negative for MCPyV and CK20." (PMID 35351092, 2022). "NMYC is not amplified and the tumor is synaptophysin-, chromogranin A- and neurofilament-positive." (PMID 33671521, 2021). "Synaptophysin was expressed in 9% of these tumours, whereas chromogranin A was negative in all." (PMID 34948181, 2021). "However, the combination of markers, as CHGA/PP, CHGA/NSE, GLUT-1/Ki-67 have been shown to increase specificity and sensitivity, to trace back to the primary tumor site and to better assess the disease aggressiveness, thus helping clinicians in therapeutic decisions." (PMID 32537434, 2020). "Moreover, at the diagnosis all tumours resulted positive for the NB markers NB84, SYP and CHGA." (PMID 31638925, 2019). "The tumor cells are diffusively positive for vimentin and S-100, focally positive for glial fibrillary acidic protein, and generally negative for epithelial membrane antigen, synaptophysin, chromogranin A, and neurofilament." (PMID 31689841, 2019). "However, the tumor cells were completely negative for other common neuroendocrine markers such as chromogranin A, synaptophysin, and TTF-1." (PMID 28103943, 2017). "The tumor stained negative for chromogranin A, trypsin, AE1/AE3, and E-cadherin." (PMID 30631803, 2015). "Blood samples demonstrated a lower chromogranin A (CgA) serum expression in mice which had been injected with NAP1L1-knockdown cells (p < 0.05) suggesting that CgA may, as in humans, be a marker of tumor burden." (PMID 25071868, 2014).
tumor (continued). "Chromogranin A is usually negative and other biomarkers related to the mucinous component or the tumor (CEA, CA-19-9, and CA-125) may be used." (PMID 23365545, 2013). "However, for detection, 5-HIAA is not as sensitive a tumor marker (specificity, 100% and sensitivity, 35%) as other markers, for example, chromogranin A (specificity, 86% and sensitivity, 68%)." (PMID 24179502, 2013). "Also we used Chromogranin A and Synaptophysin to exclude the neuroendocrine differentiation of the tumor, where we observed that, these markers were negative." (PMID 22867429, 2012). "Immunostaining further revealed that the tumor cells expressed smooth muscle actin, h-caldesmon, muscle specific actin (HHF-35), but not cytokeratin, epithelial membrane antigen, synaptophysin, or chromogranin A. Based on these findings, a diagnosis of primary pulmonary glomus tumor was established." (PMID 23050181, 2012). "The lack of CD44 in parathyroid tissues and tumours might seem unusual considering that chromogranin A expression in parathyroid neoplasms indicates neuroendocrine differentiation, and several other neuroendocrine tumours express CD44, although it is not a specific neuroendocrine marker." (PMID 35805976, 2022). "Two monoanalytes, plasma chromogranin A (CgA) and urine 5-hydroxyindoleacetic acid (5HIAA) are used to monitor the course of these neoplasms during treatment of non-curable tumours, and may also have a role in detection of recurrence after potentially curative surgery or other treatments." (PMID 33244704, 2021). "Also the regularly monitored tumor marker levels of chromogranin A and serotonin had been stable over the last months and were not indicative of progression (chromogranin A: 215 ng/ml; normal range <100 ng/ml and serotonin: 394 ng/ml; normal range 40–400 ng/ml)." (PMID 27519265, 2016). "Furthermore, our study suggests the possible use of HIF1α expression as a better screening tool for the development of CRPC than other biomarkers of CRPC such as chromogranin A (CgA) or circulating tumor cells, because of its high sensitivity and negative predictive value." (PMID 23342109, 2013). "Tumor markers CEA and CA 19-9 were not elevated at admission but chromogranin A was not available emergently." (PMID 40869648, 2025). "In our case, the tumor exhibited positive staining for CK5/6, P40, P63, and CK7, while showing negative staining for Napsin A, TTF-1, CD56, Chromogranin A, Synaptophysin, Pax-8, thyroglobulin, and vimentin." (PMID 40061900, 2025). "The tumor cells expressed NSE and cytokeratin AE1/AE3, but were immunohistochemically negative for synaptophysin, chromogranin A, calcitonin, S-100 protein, GFAP, NFH, and MAP-2, which in our opinion supports the diagnosis of NEC." (PMID 39974159, 2025). "Results of tumor markers were obtained, demonstrating negative CEA, CA 19-9, and AFP levels and elevated chromogranin A and 5-HIAA levels." (PMID 40718311, 2025). "SMARCA4 expression was positively correlated with multiple NE genes including SYP, CHGA, INSM1, DLL3 and NCAM1 and negatively correlated with non-NE factors REST, NOTCH2, and YAP1 in both SCLC cell lines and patient tumor databases." (PMID 39080761, 2024). "The tumor cells expressed CD99, synaptophysin, CD56, MUC4, and EMA (focal), but not AE1/AE3, S100, smooth muscle actin, desmin, CD34, chromogranin A, GFAP, NKX2-2, PAX7, and INSM1." (PMID 39249507, 2024). "By IHC, the tumor cells in this dural region were positive for AR (diffuse) and PD-L1 (patchy, tumor proportion score 5%) without significant reactivity to INSM1 and CHGA." (PMID 39349591, 2024). "The original tumor was histologically pure SCCC, positive for neuroendocrine markers such as synaptophysin, chromogranin A, and CD56, and negative for Alcian blue staining." (PMID 36691316, 2023).